PINK1 (PTEN induced kinase 1)
Diseases named in the same sentence as PINK1 in open-access papers (continued):
Sharing a sentence is not in itself a finding about the gene and the disease.
renal carcinoma (5 papers, 2019 to 2025). A carcinoma arising from the epithelium of the renal parenchyma or the renal pelvis. "We showed that HEY1 was significantly over-expressed in HCC, ICC, and renal cancer while PINK1 was significantly under-expressed in these three cancer types in which HIF was often activated." (PMID 31819034, 2019). "In contrast, its upregulation in renal cancers, such as KIRC and KIRP, suggests that PINK1 may have context-dependent protective effects." (PMID 40565152, 2025). "Moreover, PINK1 silence downregulates the autophagy receptor p62, inhibiting mitophagy and promoting renal cancer cell proliferation, which suggests that the role of KAT8 in activating the PINK1 signaling pathway could induce cancer cell autophagy and influence tumor cell proliferation." (PMID 40508066, 2025). "As PINK1 is also under-expressed in a HIF- dependent cancer type, renal cancer, we believe that our finding is not restricted to HCC but a universal metabolic adaption response that is beneficial to tumor growth." (PMID 31819034, 2019).
sarcopenia (5 papers, 2022 to 2025). Progressive decline in muscle mass due to aging which results in decreased functional capacity of muscles. "This study confirms that MFG‐E8 is up‐regulated during diabetic sarcopenia process and it inhibits mitophagy by down‐regulating Parkin, PINK1, and LC3B‐II/I ratio." (PMID 38553831, 2024). "Results of our study also confirmed that after treatment of berberine in IR mice with sarcopenia, the expression level of mitochondrial autophagy related molecules (PINK1 and Parkin) was significantly up-regulated." (PMID 37483428, 2023). "In general, decreased levels of mitophagy markers such as PINK1, parkin BNIP3, NIX, PHB2, FUNDC1, and AMBRA1 are associated with a reduced quality of life in sarcopenia associated with aging." (PMID 36561214, 2022). "Thus, our results reveal the mechanism under the effect of berberine on sarcopenia IR via PINK1/Parkin-inducing mitophagy, which provides a new paradigm to develop promising therapeutic strategies for sarcopenia IR." (PMID 37483428, 2023). "As sarcopenia progresses, the expression of MFG-E8 increases, which hinders the process of mitophagy by reducing the levels of important components like Parkin, PTEN-induced kinase 1 (PINK1), and microtubule-associated proteins 1A/1B light chain 3B (LC3B)-II/I ratio." (PMID 39335609, 2024). "In addition, reduced levels of mitophagy markers such as PINK1, Parkin, BNIP3, NIX, PHB2, FUNDC1, and AMBRA1 negatively impact sarcopenia-related muscle weakness and the quality of life in the elderly." (PMID 36561214, 2022).
allergic rhinitis (4 papers, 2023 to 2026). Inflammation of the nasal mucous membranes caused by an IgE-mediated response to external allergens. "In human nasal epithelial cell stress-based and mouse allergic rhinitis models, Polydatin ameliorated mitochondrial damage through PINK1-Parkin-mediated mitochondrial autophagy and exerted a protective effect against allergic rhinitis by inhibiting NLRP3 inflammatory vesicles." (PMID 38054830, 2023). "Interestingly, it has been recently demonstrated that, in allergic rhinitis, Polydatin inhibits mitochondrial damage and mitochondrial ROS by promoting PINK1-Parkin-mediated mitophagy similarly to what we showed for A5+." (PMID 37998340, 2023).
brain tumor (4 papers, 2016 to 2025). "Some PD genes, including PARK1/4, PINK1, and PARK9 (ATP13A2), have already been detected to be associated with brain tumors, indicating that the same mutations can lead to pathological changes in both PD and brain tumors." (PMID 33066407, 2020). "Furthermore, The study revealed that atypical Notch signaling interacts with PTEN-induced kinase 1 (PINK1), influencing mitochondrial function and activating the mTORC2/AKT signaling pathway, which supports the maintenance of brain tumor stem cells." (PMID 41050674, 2025). "Authors have discovered that non-classical Notch signaling interacted with PTEN-induced kinase 1 (PINK1) to modulate mitochondrial function and induce mammalian target of rapamycin complex 2 (mTORC2)/AKT signaling, which preserved brain tumor-forming stem cells." (PMID 40429321, 2025).
emphysema (4 papers, 2022 to 2025). "Malfunctioning mitochondria and cellular senescence are associated with CS-induced pathogenesis of COPD/emphysema linked with mitophagy and PINK1/Parkin signaling." (PMID 40469988, 2025). "CSE-induced PINK1-dependent mitophagy aggravates mitochondrial damage and induces necroptosis, leading to enhanced emphysema." (PMID 40469988, 2025). "PINk1 knockout mouse models developed by researchers further confirmed that increased levels of PINk1 in COPD result in emphysema and mucous secretion upon long-time cigarette smoke exposure." (PMID 35309178, 2022).
epilepsy (4 papers, 2022 to 2024). A brain disorder characterized by episodes of abnormally increased neuronal discharge resulting in transient episodes of sensory or motor neurological dysfunction, or psychic dysfunction. "It is unclear whether PGAM5 is involved in epilepsy and is associated with PINK1-mediated mitophagy." (PMID 36618822, 2022). "Previous studies reported that carriers of digenic variants in PRKN and PINK1 develop the disease at a younger age and exhibit distinctive symptoms such as schizophrenia, facial dyskinesia, grimacing and severe dysarthria and also epilepsy and essential tremor." (PMID 38173558, 2023). "This suggests that PINK1 may be critical for increased mitophagy caused by PGAM5 in epilepsy." (PMID 36618822, 2022). "In rats with lithium–pilocarpine-induced epilepsy, targeting Pink1 and enhancing its expression reduced hippocampal damage and improved mitophagy." (PMID 39457518, 2024). "Specifically, the regulation of GLS2 mainly reverses mitophagy during the latent period of epilepsy by affecting the expression of PINK1, p62, LC3, and TOMM20, thereby reducing the occurrence of SLEs." (PMID 39404053, 2024). "PINK1 expression is increased in our epilepsy model and decreased PINK1 levels are detected in the epilepsy model after inhibition of PGAM5." (PMID 36618822, 2022). "We showed that rats with SE-induced epilepsy exhibited notably lower Pink1 levels than controls." (PMID 39457518, 2024). "The interactions between PGAM5 and PINK1 in epilepsy were further found." (PMID 36618822, 2022). "Collectively, these data revealed that PGAM5 could reduce PINK1 expression to inhibit mitophagy activity during epilepsy after AAV intervention." (PMID 36618822, 2022). "More importantly, the interaction between PGAM5 and PINK1 is found in the epilepsy model." (PMID 36618822, 2022). "The purpose of the present study was to examine whether PGAM5 affects epilepsy through PTEN-induced putative kinase 1 (PINK1)-mediated mitophagy." (PMID 36618822, 2022). "All these studies reveal that PGAM5 may regulate mitophagy in epilepsy via PINK1." (PMID 36618822, 2022).
esophageal cancer (4 papers, 2022 to 2025). A primary or metastatic malignant neoplasm involving the esophagus. "The upregulation of PINK1 in lung and esophageal cancers indicates classical mitochondrial autophagy associated with chemotherapy resistance." (PMID 38334464, 2024). "The silencing of the BCL2/adenovirus E1B 19-kDa protein-interacting protein 3 (BNIP3) in CRC and the high expression of PTEN-induced putative kinase 1 (PINK1) in esophageal cancer are associated with resistance to 5-FU-based chemotherapy." (PMID 37784019, 2023). "In 159 patients with esophageal cancer who received 5-FU- and cisplatin-based preoperative chemotherapy, high expression of PINK1 was correlated with poor response to neoadjuvant chemotherapy, thus suggesting that PINK1-mediated mitophagy contributes to resistance to 5-FU-based neoadjuvant therapy." (PMID 37784019, 2023).
fibrosis (4 papers, 2017 to 2025). the formation of excess fibrous connective tissue in an organ or tissue in a reparative or reactive process. "Masson and WGA staining revealed that cardiac fibrosis and left ventricular remodelling were attenuated in the PINK1‐Tg mice." (PMID 39763059, 2025). "A decrease in PINK1 levels in type II AECs from IPF patients, IPF lung tissue, aging mice and mice challenged with bleomycin has been associated with the development of fibrosis." (PMID 31775876, 2019).
hearing loss (4 papers, 2023 to 2025). "AG-induced hearing loss can be completely or partially prevented by reducing the expression of Ripor2, Gabarap, Lc3β, Pink1, Prkn, or Gabarapl1, as identified in this study." (PMID 39928869, 2025). "In a variety of hearing loss models, dysfunction of the Pink1/Parkin signaling pathway is closely related to hearing loss." (PMID 40667486, 2025).
Hypertension (4 papers, 2020 to 2025). The presence of chronic increased pressure in the systemic arterial system. "In the context of hypertension, studies have implicated both PINK1/Parkin and receptor-mediated mitophagy pathways (e.g., BNIP3, FUNDC1) in hypertensive organ damage." (PMID 41007357, 2025). "The aim of this study is to investigate molecular mechanisms of mitochondrial dysfunctions in hypertension-induced HFpEF as well as regulatory effects of PINK1 on mitochondrial fission." (PMID 36233236, 2022). "This study investigated molecular mechanisms of mitochondrial dysfunctions in hypertension-induced HFpEF relevant to the regulatory effect of PINK1." (PMID 36233236, 2022). "The regulation of Drp1 by PINK1 (an upstream factor of Drp1) was investigated for understanding the changes of mitochondrial fission in hypertension-induced HFpEF." (PMID 36233236, 2022). "Although regulatory mechanism of PINK1/Drp1S616/mitochondrial pathway was showed in hypertension-induced HFpEF rats, the upstream of PINK1 is still unknown." (PMID 36233236, 2022). "Here, we hypothesize that PINK1 phosphorylates Drp1S616 to improve mitochondrial fission, relieve mitochondrial dysfunctions, and slow the progression of hypertension-induced HFpEF." (PMID 36233236, 2022). "Myocardial-specific overexpression of PINK1 was achieved in hypertension-induced HFpEF rats by AAV." (PMID 36233236, 2022). "Hence, PINK1 can phosphorylate Drp1S616 to improve mitochondrial fission, relieve mitochondrial dysfunctions, and slow the progression of hypertension-induced HFpEF." (PMID 36233236, 2022). "Moreover, PINK1 myocardium-specific overexpression activated Drp1S616 phosphorylation and enhanced mitochondrial fission to slow the progression of hypertension-induced HFpEF." (PMID 36233236, 2022). "Furthermore, PINK1 myocardium-specific overexpression to animals was found to activate Drp1S616 phosphorylation and enhance mitochondrial fission, which slowed the progression of hypertension-induced HFpEF." (PMID 36233236, 2022). "The high myocardial stress stimulated the decrease of PINK1 expression; however, an improved HFpEF animal model with the reasonable sample size is required to investigate regulatory mechanisms of PINK1 given that Dahl/SS rat is a hypertension-induced HFpEF model." (PMID 36233236, 2022).
kidney cancer (4 papers, 2019 to 2025). Primary or metastatic malignant neoplasm involving the kidney. "The results from clinical cohorts showed that PINK1 was significantly positively correlated with patients and may serve as an independent predictor for overall survival in kidney cancer." (PMID 37382962, 2023). "In addition, for kidney cancer, PINK1 had a detrimental effect on RFS in only KIRP (kidney renal papillary cell carcinoma) (RFS: log rank P = 0.03)." (PMID 33244455, 2020).
leprosy (4 papers, 2016 to 2025). Leprosy is a chronic infectious disease affecting primarily the skin and peripheral nervous system. "Variants in genes such as PARK2, PARL (rhomboid-like protein associated with presenilins), and PINK1 (PTEN-induced kinase 1) are critical for mitochondrial turnover through mitophagy and increase the risk of developing leprosy." (PMID 36076909, 2022). "Our results provided several lines of evidence showing that PARL and PINK1 confer genetic susceptibility to leprosy." (PMID 27876828, 2016). "In this study, we aimed to investigate the possible association of genetic variants in the PARL and PINK1 genes with leprosy in Han Chinese." (PMID 27876828, 2016). "In this study, we found that two mitochondrial genes, PARL and PINK1, conferred genetic susceptibility to leprosy per se and/or multibacillary leprosy." (PMID 27876828, 2016). "In summary, we found that common variants of the mitochondrial genes PARL and PINK1 would confer risk to leprosy per se and/or MB." (PMID 27876828, 2016). "We confirmed that common variants in PARL and PINK1 were associated with leprosy in patients underwent NGS." (PMID 27876828, 2016). "One PINK1 SNP (rs4704) showed an association with leprosy per se when compared with healthy control population from the Yuxi area (Pdominant = 0.033), and the association survived (TT vs. TC vs. CC, Pgenotypic = 0.004; Pdominant = 0.027) when we compared the patients with the pooled controls." (PMID 27876828, 2016). "Together, our results showed that PARL and PINK1 genetic variants are associated with leprosy." (PMID 27876828, 2016). "PINK1 SNP rs4704 was associated with leprosy at the genotypic level (Padjusted = 0.004)." (PMID 27876828, 2016). "We hypothesized that mitochondrial genes PARL and PINK1 would confer risk to leprosy." (PMID 27876828, 2016). "Furthermore, PARL and PINK1 could physically interact with each other and were involved in the highly connected network formed by reported leprosy susceptibility genes." (PMID 27876828, 2016). "Among the analyzed tag SNPs in the PARL and PINK1 genes, three SNPs (rs12631031 and rs7653061 of PARL; rs4704 of PINK1) were associated with leprosy per se and/or MB." (PMID 27876828, 2016). "Defects in PINK1/Parkin-mediated mycobacterial clearance could explain the previously observed association between PINK1 and PRKN with leprosy per se." (PMID 41430073, 2025). "The mechanism by which PINK1 impacts leprosy susceptibility remains a mystery and to date, no one has reported on the requirement for PINK1 in controlling M. tuberculosis infection." (PMID 31192157, 2019). "Furthermore, deep sequencing of the PARL, PINK1 and PARK2 genes in a relatively small sample identified two PARL variants (rs3732581 [p.V212L], rs13091 [p.H216]) and one PINK1 variant (rs45530340, [p.L63]) that were associated with leprosy." (PMID 27876828, 2016). "We also sequenced the entire exons of PARL, PINK1 and PARK2 in 80 patients with a family history of leprosy by using the next generation sequencing technology (NGS)." (PMID 27876828, 2016). "Thirteen tag SNPs of PARL and PINK1 were analyzed in 3620 individuals with or without leprosy from China." (PMID 27876828, 2016).
leukemia (4 papers, 2020 to 2025). A malignant (clonal) hematologic disorder, involving hematopoietic stem cells and characterized by the presence of primitive or atypical myeloid or lymphoid cells in the bone marrow and the blood. "We analyzed the TCGA database and identified reports indicating potential mutations and differential expression of PINK1 and HSP90 across various cancer types, including leukemia, adenocarcinomas, and epithelial cell neoplasms." (PMID 39921807, 2025).
oral cancer (4 papers, 2020 to 2025). "On the other hand, zinc-oxide nanoparticles also showed increased cytotoxicity toward CAL-27 oral cancer cells by PINK1/ Parkin-mediated mitophagy." (PMID 34578551, 2021). "ZnONPs have also been observed to induce toxicity by activating PINK1/Parkin-mediated mitophagy in CAL27 oral cancer cell lines." (PMID 32235610, 2020). "Moreover, knockdown of PRKN (parkin RBR E3 ubiquitin protein ligase) or PINK1 (PTEN-induced kinase 1) abolished mitophagy in MTFP1-overexpressing oral cancer cells." (PMID 40395309, 2023).
polycystic ovary syndrome (4 papers, 2016 to 2025). A disorder that manifests as multiple cysts on the ovaries. "Targeting this pathway using small molecule PINK1 inhibitors might provide benefits to clinical therapy for anovulatory disorders such as polycystic ovarian syndrome and premature ovarian failure." (PMID 27901103, 2016). "Melatonin can enhance PDK1/Akt or PINK1/Parkin signaling in granulosa cells in polycystic ovary syndrome (PCOS) patients to alter the expression levels of the SIRT1 gene, thereby regulating mitochondrial function." (PMID 37239427, 2023). "In patients with polycystic ovary syndrome (PCOS), iron-mediated mitophagy has been found to promote ferroptosis by activating TFRC/PINK1 signaling." (PMID 36198708, 2022).
prostate carcinoma (4 papers, 2018 to 2025). A carcinoma that arises from epithelial cells of the prostate gland. "Collectively, these data suggest that PINK1 is overexpressed in olaparib-resistant cells and is associated with poor survival in advanced prostate cancer and that inhibition of PINK1 decreased cell growth and resensitized olaparib treatment." (PMID 39440945, 2024). "Additionally, worse clinical prognosis and lower survival status from the public databases were determined to be associated with abnormally upregulated PINK1 expression in two different prostate cancer cohorts." (PMID 39440945, 2024). "In conclusion, our study elucidates that GRh2 targets prostate cancer by inducing mitochondrial damage, which subsequently activates two critical pathways: PINK1/Parkin-mediated mitophagy and ferroptosis." (PMID 40919139, 2025). "This study uncovers that mitochondrial alterations and PINK1 gene overexpression contribute to this resistance in prostate cancer cells." (PMID 39440945, 2024). "This study focuses on elucidating the role of mitochondrial alterations and the PTEN-induced kinase 1 (PINK1) gene in conferring olaparib resistance in castration-resistant prostate cancer cells." (PMID 39440945, 2024). "Our study demonstrates that Ginsenoside Rh2 (GRh2) exerts potent anti-tumor effects against prostate cancer in vitro and in vivo primarily through the induction of mitochondrial damage, subsequently activating two key processes: PINK1/Parkin-mediated mitophagy and ferroptosis." (PMID 40919139, 2025). "Furthermore, overexpression of the PINK1 gene was observed in resistant cells, which was correlated with resistance to olaparib and poor clinical outcomes in patients with prostate cancer." (PMID 39440945, 2024). "Enhanced mitochondrial functionality and increased PINK1 expression in olaparib-resistant cells underscore the importance of targeting mitochondrial dynamics and PINK1 to develop more effective treatments for overcoming olaparib resistance in prostate cancer." (PMID 39440945, 2024). "Thus far, the effect of targeting PINK1 expression in the prostate cancer landscape is absent." (PMID 39440945, 2024).